OXTR (oxytocin receptor)
Diseases named in the same sentence as OXTR in open-access papers (continued):
Sharing a sentence is not in itself a finding about the gene and the disease.
Anxiety (continued). "Chronic social defeat stress has been reported to decrease expression of oxytocin receptor mRNA in the ACC, inducing anxiety-related behaviors." (PMID 35008574, 2021). "The findings of increased oxytocin receptor density in the ACC within the MIA mice is of interest, as recent studies have identified oxytocin signaling as mediating rodent empathy and anxiety behaviors through the ACC." (PMID 30629642, 2019). "In addition, the extended OXTR cumulative genetic risk score was also significantly associated with total MSAS scores (p = 0.039∗, R2 = 3.6%) and the subscale measuring maternal separation anxiety from the infant (p = 0.022∗, R2 = 3.6%); however, this association was mainly driven by SNP rs968389." (PMID 27872764, 2016). "We also found that HFS of PVNOXT neurons did not affect mice's anxiety‐like behaviors in the presence of OXTR inhibitor L‐368899." (PMID 40468614, 2025). "Activation of PVNOXT promoted the release of oxytocin into the mPFC and optogenetic activation of PVNOXT terminals in the mPFC did not affect mice's anxiety‐like behaviors in the presence of OXTR inhibitor L‐368899." (PMID 40468614, 2025). "Specifically, anxiety symptoms of OXTR rs13316193 C-carriers were not so severe as those in schizophrenia patients with OXTR rs13316193 TT genotype." (PMID 38184684, 2024). "There was a significant interaction between OXTR rs2254298 and alcohol dependence level on anxiety (B = 0.23, 95% confidence interval [CI]: 0.01–0.45) but not on depression (B = −0.06, 95% CI: −0.30 – 0.18)." (PMID 37520225, 2023). "This study reveals a gene–environment interactive effect between OXTR rs2254298 and alcohol withdrawal on anxiety but not depression." (PMID 37520225, 2023). "The way OXTR- and D2R-mediated neurotransmissions interact to elicit facilitatory interactions with relevance for anxiety within the amygdala is not entirely clear." (PMID 37900160, 2023). "Using optogenetic techniques and electrophysiological recordings, OXTR interneurons (OXTRINS) of mPFC was found to modulate anxiety behavior in male mice, but not in female mice." (PMID 38017588, 2023). "The OXTR participates in social processes and underlying traits of anxiety and depression, with little evidence for the effect of the OXTR SNPs in the etiology of clinical expressions of anxiety and depression." (PMID 37520225, 2023). "OXTR rs2254298 and alcohol dependence level significantly affected anxiety symptoms that were not present in depression." (PMID 37520225, 2023). "Specifically, rs2254298 GG carriers with AUD may have higher OXTR methylation, lower OXT levels, less secure attachment, and higher anxiety levels during alcohol withdrawal." (PMID 37520225, 2023). "Specific local OXTR knockout in the raphe serotonin neurons was not sufficient to induce anxiety-like behavior in male mice, which was consistent with others' studies." (PMID 37153633, 2023). "Oxytocin injection (male rats) and activation of oxytocin receptor-expressing neurons (male mice but not female mice) in the prelimbic prefrontal cortex have been shown to decrease anxiety-related behavior." (PMID 35008574, 2021). "Additionally, childhood abuse in humans interacts with OXTR DNA methylation in both MT2 and exon 3 to predict anxiety and depression." (PMID 33516250, 2021). "In the rat medial PFC (mPFC), OT attenuates anxiety-like behavior by direct action on the OT receptor (OXTR) as shown by the use of an antagonist to the OXTR, and the lack of OXTR gene." (PMID 32616625, 2020). "OT, as the endogenous ligand of OXTR, exerting effects via OXTR, has been shown to improve social symptoms in ASD patients by intranasal administration due to its roles in regulating social behavior and improving anxiety." (PMID 33134294, 2020). "We aimed to determine whether OXT was involved with isolation-induced behavioral abnormalities such as depression and anxiety-related behaviors and whether OXT acts on the CeA that contains abundant expression of OXTR." (PMID 30158853, 2018).
Anxiety (continued). "The three OXTR gene SNPs did not interact with childhood maltreatment in predicting lifetime depression and anxiety diagnoses or sensitivity." (PMID 28353027, 2017). "We found that bilateral infusion of a highly specific oxytocin receptor antagonist (OTR-A) into the prelimbic (PL) region of the mPFC increased anxiety-like behavior in postpartum, but not virgin, females." (PMID 25147513, 2014). "However, unlike the anxiety symptoms, alcohol dependence level and OXTR rs2254298 had non-significant interaction in depression symptoms (β = −0.04, p = 0.16)." (PMID 37520225, 2023). "However, it was proved that total OXTR knockout (OXTR−/−) or local knockout in the forebrain (OXTRFB/FB) did not affect the anxiety-like behavior and sucrose intake that was used to test the depression-like behavior." (PMID 37153633, 2023). "Additionally, the OXTR−/− dams in the postpartum period had no predominant anxiety- and depression-like behaviors." (PMID 37153633, 2023). "Very interestingly, prenatal OXTR deficiency potentiates maternal diabetes-mediated anxiety-like behavior while again having little effect on ALB, which is consistent with previous findings that OXT is associated with anxiety, but not necessarily with ALB." (PMID 33633538, 2021). "Activation of oxytocin receptor-expressing neurons in the lateral septum projecting to the horizontal diagonal band of Broca has been shown to induce anxiety-related but not depressive-like behaviors via GABA in mice, suggesting anxiogenic action of the oxytocin receptor in the lateral septum." (PMID 35008574, 2021). "Next, we showed that intracentral amygdala (CeA) injection of oxytocin (OXT), but not intracerebroventricular injection, attenuated isolation-induced depression and anxiety-related behaviors via oxytocin receptor (OXTR), not vasopressin-1a receptor (V1aR), in the FST and EZMT, respectively." (PMID 30158853, 2018). "CRH-BP modulation of CRH-R1 activity on pyramidal neurons may mediate anxiety-like behavior, as conditional knockdown of CRH-BP in oxytocin receptor interneurons in the mPFC increased anxiety in male (but not female) mice." (PMID 29066956, 2017). "Therefore, our intention is to investigate in a large Caucasian sample from the Netherlands Study of Depression and Anxiety (NESDA), whether OXTR SNPs interact with experiences of childhood maltreatment in predicting clinically diagnosed lifetime depression and/ or anxiety disorders." (PMID 28353027, 2017). "While studies in non-clinical population suggest the OXTR gene may interact with early life stress in the development of depressive and anxiety symptomatology, here we show that OXTR SNPs are not involved in moderating the effects of early life stress on lifetime anxiety and depressive disorders." (PMID 28353027, 2017).
autism (88 papers, 2009 to 2026). Persistent deficits in social interaction and communication and interaction as well as a markedly restricted repertoire of activity and interest as well as repetitive patterns of behavior. "Meta-analyses of autism genetics have revealed several significant risk alleles, including some associated with the oxytocin receptor gene (OXTR)." (PMID 41255981, 2025). "Evidence has repeatedly linked the polymorphisms of the OXTR gene, particularly the rs2254298, rs2268491, rs2268498, and rs53576 SNPs with autism, empathy, and social and emotional processing." (PMID 38553454, 2024). "An interesting observation is that some SNPs in OXTR appeared to be risk factors in different populations for Chinese and Caucasian patients with autism." (PMID 36835321, 2023). "Significant controversies appeared in the interpretation of the results of genetic polymorphism studies on the possible contribution of the OXTR gene variants to the development of autism." (PMID 36835321, 2023). "Increasing evidence has shown that genetic variations, epigenetic modification states, and the expression of OXTR have been implicated in psychiatric disorders characterized by social deficits, especially in autism." (PMID 37153633, 2023). "Nevertheless, such an inconsistency raised doubts on the association of OXTR polymorphisms with autism risk." (PMID 36835321, 2023). "Single nucleotide polymorphisms (SNPs) in the OXT receptor (OXTR) gene are associated with autism, and include rs2268491(C/T), rs2254298 (G/A) and rs53576 (G/A)." (PMID 35316293, 2022). "Variations in the OXTR gene were first linked to human mental health, specifically in autism research, that extended the work demonstrating the links between the OXTR and sociability in voles." (PMID 34256847, 2021). "Another study also reported a significant correlation between OXTR -rs237902 polymorphism and severity of autism in a subpopulation of Turkish subjects." (PMID 33712060, 2021). "Studies have implicated OXTR genotypes in conferring either a risk or protective effect in autism, schizophrenia, and eating disorders (ED)." (PMID 34256847, 2021). "In humans, hyper-methylation of OXTR is associated with decreased OTR expression in the temporal cortex of autism patients, implicating the epigenetic regulation of OXTR in the pathogenesis of neuropsychiatric disorders." (PMID 34576011, 2021). "Oxytocin receptor (OTR) desensitization followed by downregulation by oxytocin in the fetal brain was proposed as a possible cause of the offspring autism development." (PMID 31379974, 2019). "Here, we focused specifically on the oxytocin receptor (OXTR) gene, as it has been previously linked with social cognition and behaviour in the typical population, as well as with autism." (PMID 30918622, 2019). "Single nucleotide polymorphisms (SNPs) in the OXTR have been associated with autism in different populations, especially related to the social domain in autism, although null-findings are also reported." (PMID 30918622, 2019). "The rs2254298 SNP has been associated with autism, attachment behavior, and depression and rs2254298 and rs53576 were the most informative among 27 OXTR SNPs in a small sample of 38 subjects to predict responses to oxytocin in autism." (PMID 29912955, 2018). "In contrast, reduced OXTR DNAm has been associated within indicators of perinatal stress, postnatal depression, social anxiety and autism in children." (PMID 29843655, 2018). "The OXTR 3′ polymorphism rs7632287, previously related to social bonding behavior and autism risk, was associated with participants’ ability to recognize faces." (PMID 27713694, 2016). "Positive association of the OXTR gene with autism has been demonstrated in the Chinese Han population." (PMID 26738630, 2016). "Other authors have associated depression and anxiety with the OXTR rs2254298 polymorphism in adults, and with autism in children." (PMID 26738630, 2016).
autism (continued). "Methylation of oxytocin receptor gene (OXTR) has been associated with autism, psychopathy, acute psychosocial stress in the population experienced war adversities early in life and anorexia." (PMID 27903255, 2016). "Single nucleotide polymorphisms in OXTR gene have been significantly correlated to autism in a meta-analysis and have also been correlated to Asperger’s syndrome in a separate study." (PMID 26273428, 2015). "In Japanese and Chinese populations, the rs2254398 A allele of OXTR has been reported to be linked to autism." (PMID 26599592, 2015). "Two other studies reported an association between genetic variations in OXTR and autism-related phenotypes: empathy and mind-reading." (PMID 25264479, 2014). "OXTR methylation has also been associated with autism, but variation within normal human aged population has not, to our knowledge, previously been shown." (PMID 24112369, 2014). "Recent studies have reported additional SNPs in the human OXTR gene, linked with empathy and autism, indicating that it is a more complex interaction affecting behavioral differences and that it is still unclear which precise mechanisms are involved." (PMID 25405348, 2014). "Previous studies have demonstrated that the methylation status of the promoter region of this gene is associated with tissue-specific OXTR expression and the development of autism, a disorder linked to PTB." (PMID 23533356, 2013). "There is first evidence that OXTR methylation is associated with autism, high callous-unemotional (CU) traits, and differential activation of brain regions involved in social perception." (PMID 23734094, 2013). "DNA methylation is a major epigenetic mechanism that regulates gene transcription, and has been linked to reduced expression of the oxytocin receptor in individuals with autism." (PMID 23441222, 2013). "There is first evidence that OXTR methylation is associated with autism, high callous-unemotional traits, and differential activation of brain regions involved in social perception." (PMID 23734094, 2013). "Behavioral studies indicate that the OXTR gene is associated with trait reward sensitivity and social motivation deficits in autism." (PMID 24348360, 2013). "DNA methylation is a known epigenetic mechanism of gene silencing and in this same study, increased methylation was associated with decreased OXTR gene expression in the temporal cortex of autism cases." (PMID 23226454, 2012). "Previous studies reported associations between OXT and OXTR genetic polymorphisms and risk for disorders characterized by impaired socio-emotional functioning, such as schizophrenia and autism." (PMID 23284802, 2012). "It is conceivable that a methylation promoting agent accumulates in a parent over time leading to increased silencing of the OXTR gene across susceptible offspring and therefore resulting in increased severity across autism birth order." (PMID 23226454, 2012). "In humans, the OXTR gene, localized as a single copy on chromosome 3, has been implicated in the development of autism, a phenotype characterized by deficits in social behavior and language development." (PMID 20585395, 2010). "Further studies have examined the association between single SNPs in the OXTR gene and autism, with mixed results." (PMID 20585395, 2010). "Several independent studies identified the 3p25 region, where the OXTR gene is localized, as linked to autism." (PMID 20585395, 2010). "We chose to focus on the deletion in chromosome 3p25.3 because of previous reported linkage to the region, association data implicating the oxytocin receptor (OXTR) that is contained within the deletion to the etiology of autism." (PMID 19845972, 2009). "The discovery that a five-locus haplotype block, rs237897-rs13316193-rs237889-rs2254298-rs2268494, is considerably associated with autism corroborated the proposal that specific genetic variants of OXTR may be risk factors for this disease." (PMID 36835321, 2023).
autism (continued). "Importantly, the same SNPs were subsequently tested in Caucasian patients and the results supported the conclusion about the association of OXTR with autism." (PMID 36835321, 2023). "However, there are discrepancies in conclusions about roles of the OXTR gene polymorphisms as risk factors for autism." (PMID 36835321, 2023). "An association between autism and two SNPs (rs2254298 and rs53576) was found, providing a basis for suggesting that impaired OXTR function might contribute to the development of the disease." (PMID 36835321, 2023). "An association between some OXTR variants with unipolar depression was demonstrated, but the interesting point is that this concerned rs53576 and rs2254298, the same SNPs which were suggested to play a role in the development of autism." (PMID 36835321, 2023). "The studies conducted with a large number (over 340) of autistic patients indicated that two SNPs in OXTR, which were controversial in their connection to the susceptibility to autism rs53576 and rs2254298, were associated with an increased severity of social deficits." (PMID 36835321, 2023). "Therefore, despite the presence of published results suggesting the contribution of OXTR variants to the development of autism, the question about the importance of OXTR in this disease remains still unanswered." (PMID 36835321, 2023). "Furthermore the OXTR SNPs rs2254298 (G/A) and rs53576 (G/A) are found associated with autism in the Chinese Han population and rs2254298 in Caucasian patients." (PMID 35316293, 2022). "A recent report has indicated that developmental exposure to PM2.5 caused autism-like behaviors, such as poor social interaction and repetitive behavior, accompanied by lower oxytocin receptor (OXTR) protein level, catalase activity, and glutathione (GSH) concentration, in 7-week-old male rats." (PMID 33430368, 2021). "The hypothesis that variation in the OXTR was associated with deficits in social behaviour was substantiated by a study linking rs53576 and rs2254298 to autism." (PMID 34256847, 2021). "Previous studies revealed that OXTR is associated with social cognition in autism." (PMID 31996222, 2020). "One of the genes implicated in autism is the oxytocin receptor (OXTR)." (PMID 30918622, 2019). "In a meta-analysis of 48 studies associating the OXTR rs53576 polymorphism with different aspects of social functioning, including personality, social behaviour, psychopathy and autism (n = 17 559), Bakernans-Kranenburg found a combined effect size of r = .02 (p = 0.07)." (PMID 30365517, 2018). "In line with the direction of the current association, two studies have reported an association between the G allele and autism spectrum disorder, and a meta-analysis showed the association between rs7632287 and autism to be the most robust amongst OXTR polymorphisms." (PMID 27713694, 2016). "However, in Caucasian autism trios, the rs2254395 G allele of OXTR was overtransmitted to probands with autistic disorders." (PMID 26599592, 2015). "A third hypothesis is that the pattern of methylation in the MT2 region of the OXTR gene in patients with AN is similar to that seen in autistic disorders and that the methylation status might be linked to the intensity of autistic traits." (PMID 24523928, 2014). "Regarding variation in the oxytocin receptor gene (OXTR) gene, two polymorphisms are of particular interest: rs53576 has been associated with variance in empathic performance in healthy populations, and is implicated in the etiology of autism." (PMID 25538588, 2014). "Finally epigenetic studies show that different methylation patterns in OXTR are involved in the predisposition to classic autism and variability of social perception." (PMID 25264479, 2014). "Behavioral research shows that OXTR is associated with the ability to comprehend information during vocal communication and with the severity of communication deficits in autism." (PMID 24348360, 2013).